CD4 (CD4 molecule)
Diseases named in the same sentence as CD4 in open-access papers (continued):
Sharing a sentence is not in itself a finding about the gene and the disease.
tumor (continued). "Importantly, combined OK-432- and PSK-activated DC/tumor showed superior efficacy in inhibiting CD4+CD25+Foxp3+ T cell generation, in comparison to those single activated or un-activated DC/tumor." (PMID 23555011, 2013). "Rejection of dnIFN-γ Rα MMC tumor cells was consistent with our previous observation showing that sorted IFN-γ Rα negative MMC tumor cells were rejected by CD4-depleted FVB mice." (PMID 24324806, 2013). "However, theelevation of CD4+ and CD8+ immune cell populations we observed inCOX-2MECKO mice, prompted us to consider how tumor cell COX-2 contributesto tumor immune function." (PMID 24004819, 2013). "Rejection of dnIFN-γ Rα MMC by CD4-depleted FVB mice was consistent with our previous observation showing that sorted IFN-γ Rα negative MMC tumor cells were rejected by CD4-depleted FVB mice." (PMID 24324806, 2013). "Transduced L23 cells were labeled with CMFDA and T cells were separated after exposure to the tumor cells distinguishing the green-fluorescent from the non-fluorescent CD4+ T cells." (PMID 24205259, 2013). "In addition, LIGHT expression was decreased in both CD3+ (41% vs. 31%) and CD4+ (41% vs. 32%) T-cells and minimally expressed in CD8+ cells (<1%) from peripheral blood mononuclear cells in tumor bearing mice compared to controls." (PMID 23514280, 2013). "Since cooperation of CD4 and CD8 T cells appears important in the effector phase of an anti-tumor response and may contribute to the bystander elimination of tumor stroma, it may be worthwhile to simultaneously target MHC class I and II targets." (PMID 24265631, 2013). "Most likely, a direct anti-tumor effect of CD4+ T cells is not required in a system in which the cytotoxic function of CD8+ T cells is sufficient to mediate the successful rejection of the tumor." (PMID 22890822, 2013). "In marked contrast, depletion of CD4+ T cells 5 days post-tumor challenge and one day prior to vaccination did not significantly alter the therapeutic efficacy of these vaccines." (PMID 24066030, 2013). "Depletion of CD8+ T cells, but not CD4+ T cells, resulted in more aggressive tumor growth in otherwise protected mice." (PMID 23671644, 2013). "Anti-tumor immunity to aberrant self-antigen (tumor antigen) is prioritized in cellular immunity, and requires the interplay of a variety of accessory and major effector cells including CD8+ and CD4+ T cells." (PMID 24350772, 2013). "Interestingly, pharmacologic blockade of IDO leads to enhanced IL-6 production by pDC that converts tolerogenic CD4+ Tregs into TH17-like cells, and this conversion correlates with enhanced CD8+ T cell activation and anti-tumor immunity." (PMID 23874338, 2013). "Tumor CD4+ T cell infiltration was not significantly altered by either gemcitabine or anti-CTLA-4, although ICOS expression as a marker of activation was decreased in all gemcitabine-treated mice, either with or without anti-CTLA4." (PMID 23626745, 2013). "The tumor cells were only weakly positive for CD22 and CD30, but strongly positive for CD4." (PMID 23880011, 2013). "However, when tumor-bearing animals receive an adoptive transfer containing wild-type CD8+ T cells and Ebi3−/− CD4+ T cells, the growth of these tumors was reduced by approximately 50%." (PMID 24151492, 2013). "It has been an accepted hypothesis that most of the anti-tumor responses are mediated by CD8+ T cells and CD4+ T cells are restricted either to help CD8+ T cells for effective cytotoxicity or prime dendritic cells (DC) to enhance the response of CD8+ T cells." (PMID 24205259, 2013). "From previous work, we knew that CD4+ T cells can help rejection of tumors through indirect effects on NK cells and tumor-infiltrating macrophages and Tregs can negatively influence this help by inhibiting IFN-γ synthesis." (PMID 22890822, 2013).
tumor (continued). "In contrast, although there was a trend toward increased numbers of IL-4 and IL-17 producing tumor antigen-specific CD4 T cells both systemically and locally, these trends were not statistically significant." (PMID 23557194, 2013). "Immunohistochemical results showed, in all treated tumors, a significant increase in the intratumoral CD4+ and CD8+ T cells that are the major lymphocyte populations involved in the antitumor priming and tumor rejection in vivo in addition to a significant decrease in the intratumoral MDSCs." (PMID 24156020, 2013). "We separated fluorescent and non-fluorescent CD4+ T cells after exposure to CMFDA-labeled tumor cells and isolated cells were cultured without any further stimulation in medium for 5 days." (PMID 24205259, 2013). "Higher frequencies of CD4+ and CD8+ T cells were observed in both the center and border zones of the tumors treated with RdB/IL23/p35 when compared with RdB/IL12- or RdB/IL23-treated tumor tissues." (PMID 23844018, 2013). "In order to demonstrate that tumor rejection in mice depleted for CD8+ T cells and Tregs was due to effector CD4+ T-cell responses, tumor growth was tested in mice lacking both CD4+ (including Tregs) and CD8+ T cells." (PMID 22890822, 2013). "We found that IL-17 was predominantly produced by γδ T cells rather than CD4+ T cells or CD8+ T cells infiltrated into the tumor tissues." (PMID 24453427, 2013). "CRLM CD4+ subsets were decreased both in total and when calculated as a percentage of CD3+ cells, corresponding with decreased expression of CD3+ and CD4+ cells in CRLM on microscopy of independent tumor sections." (PMID 23514280, 2013). "In late-stage Tg-neu tumors, Lov treatment did not alter total numbers of tumor-associated leukocytes (not shown), but selectively enhanced infiltration of cytotoxic CD8+ and to a lesser extent, of CD4+ and double-negative T cells." (PMID 24317954, 2013). "Under both scenarios, IL-10 may influence tumor cells through the development, recruitment, and/or activation of various immune response cells, including tumor-reactive CD8 and other CD4 effector T cell subsets." (PMID 23533029, 2013). "Again, CD8+ T-cell depletion alone did not influence the functional CD4+ T-cell response during tumor rejection." (PMID 22890822, 2013). "With curcumin before tumor development in the combination therapy, the production of IL-6 was significantly decreased and IL-12 increased by myeloid-derived suppressor cells (MDSC), in correlation with improved CD4 and CD8 T-cell responses in blood." (PMID 24156030, 2013). "Therefore, we analyzed the expression of activation markers on CD4+ and CD8+ T cells 7 and 15 days after tumor cell injection." (PMID 24098720, 2013). "So as to investigate the relative contribution of the two distinct lymphocyte subpopulations in the early processes leading to tumor eradication with the G-G schedule treatment, groups of 10 BALB/c mice were deprived of CD4+ or CD8+ T cells by specific mAb injection according to the protocol." (PMID 24156020, 2013). "Both CD4+ and CD8+ T cells are required for effective tumour cell elimination." (PMID 23349906, 2013). "Flow cytometry demonstrated that high expression of CD25 was observed in CD4+ T cells stimulated by OPK-DCs fused to all types of tumor cells (data not shown)." (PMID 23555011, 2013). "Our data demonstrated that intratumoral co-administration of SLC and anti-CD25 mAbs was an effective treatment for HCC, which was correlated with the altered tumor microenvironment and systemically optimized percentages of Tregs, CD8+ T cells and CD4+ T cells in peripheral immune organs." (PMID 24304581, 2013). "Elevated levels of Breg disturbed in tumor could transform CD4+ Treg into FoxP3+Treg via direct interaction with transforming growth factor-beta (TGF-beta) pathways, resulting in tumor proliferation." (PMID 23825635, 2013). "Deletion of CD8+, CD4+ or NK cells did not affect tumour growth in the absence of EW-7197 treatment." (PMID 24127404, 2013).
tumor (continued). "Using a Cre/flox-based system in mouse models, it has been observed that, in the absence of TGF-β1 produced by activated CD4+ T cells and regulatory T cells, there is inhibition of tumor growth and protection from spontaneous PCa." (PMID 23738079, 2013). "We showed that APC-stimulated CD4+ helper T (Th) cells are able to stimulate naïve CD8+ T cells via acquired peptide-major histocompatibility complex-I (pMHC-I) complexes, inducing central memory CTL stimulation and anti-tumor immunity." (PMID 23785406, 2013). "CD4+CD25high Treg cells from cancer patients effectively inhibit NK cell-mediated cytotoxicity and the depletion of CD4+CD25+ Treg cells enhances NKT cell-mediated anti-tumor immunity in a murine mammary breast cancer model." (PMID 23378947, 2013). "The majority of tumor-derived Tim-3+ CD4 T cells exhibited an impaired capacity to produce IFN-γ and IL-2, but expressed higher levels of CD25, Foxp3, CTLA-4 and GITR than their Tim-3− CD4 T cell counterparts." (PMID 23526963, 2013). "It was previously reported that CD8+ T cells are essential in controlling FBL-3 progression, whereas CD4+ T cells did not affect the tumor growth." (PMID 22890822, 2013). "At first, DC vaccination protocols mainly focused on targeting cytotoxic CD8+ T cells, but it has become clear that CD4+ T cells not only augment the induction and proliferation of these CD8+ T cells, but also participate in the elimination of tumor cells and maintenance of long-term immunity." (PMID 24348481, 2013). "Paradoxically, several experimental and clinical observations have recently shown that these same CD4 effector cell subsets and their signature cytokines can not only contribute to antitumor responses but also tumor-promoting activities." (PMID 23533029, 2013). "The AbN of CD4+ CD25+ CD152+ Tregs in the patients with good and poor pathological tumour responses to 8 cycles of NAC showed significant reductions in circulating levels after chemotherapy, compared with pre-treatment levels, (p = 0.020, p = 0.010, respectively)." (PMID 23320561, 2013). "It revealed that CD11c+, CD4+, and CD8+ cells were remarkably infiltrated into tumor by UV-Tianjin." (PMID 24007528, 2013). "The findings of tumor infiltrating CD8 and CD4 immune cells in the tissues from relapse-free patients is consistent with earlier reports on the reduction of CD8+ and CD4+ cells as highly predictive of local recurrence of CRC while their presence associated with longer recurrence free survival." (PMID 24312117, 2013). "The experimental approaches based on the sorting of CD25−T-cells do not provide supportive evidence for a de novo induction of pTregs, and do not exclude a possibility of tumor-driven activation and expansion of CD4+CD25−Foxp3+ thymus-derived tTregs." (PMID 24133490, 2013). "Presentation of tumor antigens to killer T cells (CD4+/CD8+) through MHC molecules in the presence of inflammatory cytokines can thus lead to generation of a robust and long-lasting immune responses directed against the tumor." (PMID 24062768, 2013). "Because the mechanism of CD4+ cells role in anti-tumor activity is not well defined, it is not yet clear what type of in vitro assay would provide an optimal surrogate marker of an effective immune responses." (PMID 24273748, 2013). "In contrast, the depletion of CD4+ T cells did only temporary increase the tumor size at 6 days ptc but did not affect the subsequent rejection of FBL-3 tumor cells." (PMID 22890822, 2013). "To test if this TGFβ production by tumor cells may be responsible for Treg accumulation in BLM-treated mice, we sorted CD4+ GFP+ from Foxp3-EGFP mice and stimulated them with T cell receptor (TCR) triggering." (PMID 23762310, 2013). "Of note, the observed interaction of T cells with tumor cells required no bystander cells as exemplified by exposure of highly purified CD4+ T cells to L23 cells." (PMID 24205259, 2013).
tumor (continued). "Immune function is generally compromised in cancer patients, which have lower absolute numbers of peripheral blood lymphocytes but increased numbers of functionally suppressive CD4+CD25+ Treg and dysfunctional dendritic cells (DC) in peripheral blood and tumor microenvironment." (PMID 23861693, 2013). "The majority of CD4+ T cells favor tumor progression, while CD8+ T cells favor tumor rejection." (PMID 24273748, 2013). "Next, we wanted to analyze functional properties of CD4+ and CD8+ T cells during tumor rejection." (PMID 22890822, 2013). "Our own observations in the B16 melanoma model have revealed that natural Tregs are the major subset recruited into the tumor microenvironment rather than conversion of FoxP3-negative CD4+ T cells." (PMID 24829752, 2013). "Paradoxically, several experimental and clinical observations have recently shown that such CD4 effector cell subsets and their signature cytokines can not only contribute to effective antitumor responses but also facilitate tumor-promoting activities." (PMID 23533029, 2013). "To determine the induction of anti-tumor T-cell responses, we harvested the splenocytes 14 days after tumor challenge and re-stimulated purified CD4+ or CD8+ T cells with purified splenic CD11c+ cells pulsed with peptides mix (HIV gag, HER2, or neu) or NT2.5 tumor lysate." (PMID 22397502, 2012). "This was accompanied by an increase in the numbers of CD4+ and CD8+ T cells within the tumor." (PMID 22159900, 2012). "Our results indicate that CD4 T cell responses against DBY, which are unique to female immune repertoires, can markedly augment CD8 T cell responses against a spontaneously arising mutant tumor antigen such as SPAS-1." (PMID 22493742, 2012). "There was no change in the frequencies of the CD4+ or CD8+ T lymphocytes and NK cells between tumor-associated and unaffected mucosa, while the frequencies of CD19+ B cells were lower in the tumor." (PMID 22319577, 2012). "Thus, vaccine-induced CD4+ and CD8+ T cells were both essential for tumor protection and long-term survival." (PMID 22397502, 2012). "Antigen-specific CD4+ T cells were known to help the induction and maintenance of effector/memory CD8+ CTLs and also elicit direct cytotoxic activity against target tumor cells." (PMID 23028615, 2012). "CD4+CD25+FOXP3+ T regulatory (Treg) cells play an important role in the maintenance of self-tolerance and the modulation of overall immune responses against infections and tumor cells." (PMID 22489248, 2012). "Vaccine-induced CD4+ and CD8+ T cells were both essential for tumor protection." (PMID 22397502, 2012). "However, in mice with solid sarcoma EGF-SEA, CD4+, CD8+ and SEA-reactive T lymphocytes strongly suppressed tumor growth." (PMID 22375962, 2012). "Our model showed a lack of CD4 T cell infiltration into the tumor at both early and late time points indicating the Mam-A specific CD8 T cells do not require further help to enter the tumor microenvironment and cause tumor regression." (PMID 22911764, 2012). "Recently, Renaudet and coworkers showed a four-component HER-GLP vaccine construct (one CD4+ T-cell epitope, one OVA CD8+ T-cell epitope, one carbohydrate B-cell epitope and a built-in palmitic acid adjuvant) inhibited the tumor growth in HER-GLP immunized mice." (PMID 22815882, 2012). "IDO expression has been observed in primary tumors and human tumor-draining lymph nodes in proximity to CD4+CD25+ regulatory T cells (Tregs), and studies with mice have revealed an IDO-dependent differentiation of naïve CD4+ T cells into Foxp3+ Tregs." (PMID 23028625, 2012). "The authors reported induction of robust detectable immunity as evidenced by in vitro monitoring of circulating vaccine-induced antigen-specific CD4+ and CD8+ T cells, as well as both T-and B-cell infiltrates into tumor region as well as dramatic reductions in tumor volume." (PMID 22851815, 2012).
tumor (continued). "The data revealed that neither splenic (data not shown) or tumor CD4+ T cells (yielding about 35% of the immune profile) and CD8+ T cells (yielding about 10%) were altered due to COX2 expression." (PMID 23029485, 2012). "These included transcription factor EGR1 which is reported to have tumor suppressor properties, genes involved in lymphocyte activation and differentiation such as BCL6, CD4 and SMAD3 and genes TLR3 and TIRAP that are part of the toll-like receptor signaling pathway." (PMID 23072359, 2012). "In order to assess whether Tregs can be recruited to the tumor by factors released by the TM40D-COX2 cells, CD4+ CD25+ Tregs were enriched by magnetic column (MACS) from naïve thymus and lymph nodes." (PMID 23029485, 2012). "Although freshly isolated CD4+ T cells from A20-silenced Mф immunized mice display some nonspecific cytotoxicity, the isolated CD4+ T cells after in vitro re-stimulation use MHC class-II restricted mechanism to kill tumor cells." (PMID 23145026, 2012). "Similar correlation was also observed between IFN-γ-producing tumor-infiltrating CD4+ T cells and tumor growth (data not shown)." (PMID 23071764, 2012). "Indeed, all cured mice were resistant to tumor challenge and the tumor rejection was mediated by CTL and, particularly, by long-living, tumor specific CD4+ TH cells." (PMID 22849661, 2012). "Due to the significant change in the CD38+ CD4+ subset in contrast to CD8+ cells, it was further of interest to analyze whether the former would have a tumor migrating capability." (PMID 24213326, 2012). "Indeed, such a high immunoprevalence has been observed only for few tumor antigens, such as NYESO-1 and survivin., eliciting CD4 specific responses in at least half tested patients." (PMID 23284752, 2012). "In particular, the generation of both CD4+ and CD8+ central memory (CD44+ CD62Lhigh) lymphocytes, which are necessary to mediate protection in ACT recipients upon challenge with antigen expressing tumor cells, is observed." (PMID 23097673, 2012). "Although the underlying mechanism of therapy-induced inflammation has not been defined, some recent studies suggest that tumor-reactive CD4+ T cells play an important role in initiating and modifying the inflammatory milieu." (PMID 22778760, 2012). "Similarly, CD4 and CD8 T cells recognize MHC class II and class I molecules on tumor cells, respectively, and B cells produce antibodies against tumor antigens." (PMID 22359489, 2012). "CD4+ and CD8+ T cells also produced IFNγ upon re-stimulation with NT2.5 tumor lysate-pulsed DCs." (PMID 22397502, 2012). "The reduced number of TCR-transgenic SP CD4+ thymocytes and reduced percentage of peripheral CD4+ T cells (data not shown) in mice with tumor compared to tumor-free mice, independent of SH2D2A expression, is consistent with these previous results." (PMID 23144743, 2012). "Both CD4 and CD8 T cells can mediate tumor regression, and the relative contribution of each lymphocyte population may vary depending on the tumor model." (PMID 22312440, 2012). "TCR gene transfer can be used to redirect CD4 helper T cells, and these could be used in combination with CD8+ tumour specific T cells to provide help for the antitumour response." (PMID 22319532, 2012). "Thereby, we could demonstrate an increase in the number of activated CD4+ and CD8+ lymphocytes in the respective organs with increasing tumor burden." (PMID 22674057, 2012). "Both CD4+ and CD8+ T cells, may also contribute to the anticancer effect since their counts are recovered in those tumor-bearing mice treated with mirtazapine." (PMID 22808019, 2012). "Flow cytometry analyses showed that CXCR3, mainly expressed by Th1 cells and CTL, was present on significantly fewer CD4+ and CD8+ LPL (p<0.01) in the tumor tissue compared to the unaffected tissue, whereas in the case of Treg there was only a trend towards decreasing frequencies of CXCR3+ cells." (PMID 22319577, 2012).